VIM (vimentin)
Diseases named in the same sentence as VIM in open-access papers (continued):
Sharing a sentence is not in itself a finding about the gene and the disease.
lung adenocarcinoma (continued). "This study showed that treatment of A549 lung adenocarcinoma cells with a specific PRMT5 inhibitor, GSK591, suppressed the expression of TGF-β1-induced EMT protein markers such as Snail and Vimentin, treatment of T1-44 alone did not suppress the expression of PRMT5." (PMID 36765032, 2023).
sarcoma (107 papers, 2006 to 2026). A usually aggressive malignant neoplasm of the soft tissue or bone. "VIM is an epithelial cytoskeletal protein associated with the epithelial-mesenchymal transition process and it is up-regulated in sarcoma." (PMID 25978681, 2015). "Recently, it has been suggested that vimentin expression may be associated with the ability of high-grade epithelial tumors to recur as carcinosarcomas or sarcomas." (PMID 38903727, 2024). "WFA treatment causes vimentin cleavage and induces sarcoma cell apoptosis." (PMID 34022967, 2021). "Immunohistochemistry showed co-expression of cytokeratin and vimentin, supporting mixed epithelial and sarcoma-like features." (PMID 42279192, 2026). "Cytokeratin (AE1/AE3) negativity excluded epithelial malignancy, but vimentin positivity supported a sarcoma lineage." (PMID 41245941, 2025). "Vimentin is primarily used to differentiate carcinoma from sarcoma, demonstrating high sensitivity but low specificity." (PMID 40703554, 2025). "Epithelial components express markers such as CK and EMA, while stromal components express mesenchymal markers like Vimentin and occasionally sarcoma-specific markers." (PMID 40823095, 2025). "Consistent with this notion, we observed some sarcomas that showed small areas of PANCK expression among the vimentin-positive cells." (PMID 38335300, 2024). "Immunohistochemical examination showed positive expression both of epithelial cell marker CK and sarcoma-like component marker Vimentin." (PMID 38552058, 2024). "Vimentin positivity and the negativity of the cytokeratin panel supported the spindle cell morphology of the tumor as a mesenchymal tumor (sarcoma)." (PMID 39768800, 2024). "Cytokeratin (AE1/AE3) and vimentin were used as stains to further classify the tumor type as carcinoma, sarcoma, or mesothelioma." (PMID 38105775, 2023). "Conversely, if neoplastic cells are positive for only cytokeratin, it suggests carcinoma, while positivity for only vimentin indicates sarcoma." (PMID 38105775, 2023). "Vimentin, a classic marker for aggressive and invasive mesenchymal cells, most likely predicted the rapid development and early relapse of the giant sarcoma." (PMID 37635229, 2023). "Leucocyte common antigen (LCA; CD45) and desmin/vimentin are used for the differential diagnosis of lymphomas and sarcomas, respectively." (PMID 36831022, 2023). "In the poorly differentiated sarcoma, tumour cells expressed vimentin and α-SMA, suggesting possible myofibroblastic differentiation." (PMID 35454212, 2022). "Vimentin is a well-described biomarker for several cancers including sarcoma, known to be involved in the progression of liver disease and HCC." (PMID 36591611, 2022). "In three cases of poorly differentiated sarcomas, tumour cells expressed only vimentin and were classified as pleomorphic fibrosarcomas." (PMID 35454212, 2022). "The remaining cells were fixed and stained to detect vimentin, which is specific for sarcoma, or CD45 and CD14, to detect white blood cells." (PMID 34063272, 2021). "Here, for the first time reported in the literature, we have enumerated the cell surface vimentin (CSV+) CTCs in the blood of 92 sarcoma pediatric and adolescent and young adult (AYA) patients as a possible marker of disease." (PMID 34956881, 2021). "In the CS cases, most carcinoma and sarcoma cells separately resided as cytokeratin+/vimentin- and cytokeratin-/vimentin+ populations, respectively." (PMID 34172714, 2021). "With reference to 18F‐FDG PET/CT images, surgery or biopsy of a lung mass or intestinal lesion was performed, and sarcoma marker vimentin and carcinoma marker cytokeratin were finally found to be positive, which verified intestinal metastasis of PSC." (PMID 32410331, 2020).
sarcoma (continued). "The pleomorphic sarcoma showed a diffuse expression of vimentin and inhomogeneous co-expression of actin." (PMID 32349235, 2020). "Immunohistochemistry is critical to making the diagnosis of SCUP since these cases often express both broad lineage carcinoma (pancytokeratin) and sarcoma (vimentin and desmin) markers." (PMID 31623602, 2019). "Representative xenograft sarcoma samples from each cell line were evaluated for vimentin and cytokeratin expression." (PMID 30678671, 2019). "The remaining cells were fixed and stained with antibodies specific for sarcoma, vimentin, or white blood cells (WBCs), such as CD45 and CD14." (PMID 31882696, 2019). "Although vimentine is always positive in sarcomas, whereas cytokeratins are weakly and focally expressd, a vascular tumor should be suspected when diffuse and intense vimentin positivity with negativity of mesothelioma markers (ex." (PMID 31692820, 2019). "On the other hand, some types of sarcoma, such as epithelioid or synovial sarcomas, leiomyosarcomas or malignant peripheral nerve sheath tumours, can co-express vimentin and CK." (PMID 29808414, 2018). "In this case, hematoxylin and eosin staining and immunoreactivity for vimentin led us to conclude that the tumor was a sarcoma and to make a final diagnosis of MFH." (PMID 30103739, 2018). "For comparative purposes, we also tested the detection of ASPS CTCs employing specific monoclonal antibodies against ASPL-TFE3 type 1 fusion protein and vimentin, as cell-surface vimentin (CSV) has been proposed as a marker of circulating sarcoma cells." (PMID 28403214, 2017). "By focusing on CD45 to eliminate normal white blood cells, vimentin to highlight sarcomas, and visual inspection of the entire cell, including the nucleus, we are able to accurately quantify CTC from a wide variety of sarcoma histologies." (PMID 29108279, 2017). "Vimentin is an intermediate filament highly expressed in mesenchymal cells and correlated with sarcoma migration and invasiveness." (PMID 29246026, 2017). "In a cell panel representing different types of sarcoma, high sensitivity to WFA was observed linked to caspase‐dependent degradation of vimentin and apoptosis activation." (PMID 28556516, 2017). "An interesting drug against sarcomas is the naturally derived bioactive compound withaferin‐A (WFA) that targets vimentin." (PMID 28556516, 2017). "Vimentin overexpression was frequently observed in several cancers, and a cell-surface vimentin emerged as an exclusive marker for different subtypes of sarcoma, including OS." (PMID 29246026, 2017). "Common immunochemical markers for sarcoma are vimentin, keratin, desmin, leucocyte common antigen, and S100, but not CD99 and MIC2, which characterize primitive neuroectodermal components, a hallmark of immature teratomas." (PMID 27528018, 2016). "Undetermined tumours should be subjected to further immunohistochemistry, such as analysis of smooth-muscle actin, desmin, vimentin, von Willebrand factor or neuron-specific enolase, before a final diagnosis of “poorly differentiated sarcoma” should be made." (PMID 25563490, 2015). "CD56 is expressed in about 50% of the tumors and it is used to distinguish from other neuroendocrine tumors and vimentin is used to distinguish from other sarcomas." (PMID 25276456, 2014). "Intimal (spindle cell) sarcomas usually show positive immunoreactivity for vimentin, osteopontin, and MDM2." (PMID 23424592, 2013). "Further, although the sarcoma-like elements in metaplastic carcinoma acquire vimentin positivity, they still retain epithelial markers." (PMID 23964821, 2013). "With particular reference to sarcomas vimentin had an Az of 0.64 (Az 0.5 uninformative; 0.7 good; 0.8 excellent, sensitivity and specificity)." (PMID 24216705, 2013). "Immunostaining of cytokeratin and vimentin, at least, is mandatory to ascertain the diagnosis if secondary sarcoma is suspected." (PMID 22953099, 2012).
sarcoma (continued). "A natural compound, withaferin-A-induced vimentin degradation and slowed the growth of sarcomas and had proapoptotic effects in sarcoma and carcinoma cell lines expressing vimentin." (PMID 21448168, 2011). "It consists of laboratory testing: red blood cells sedimentation rate, lactic dehydrogenase, creatin kinase, alkaline phosphatase, anti-vimentin, anti P100 antibodies and anti-sarcoma antibodies serum levels." (PMID 20108507, 2008). "Immunohistochemical studies revealed diffuse positivity with S-100 protein, and negativity with Desmin and Vimentin, thus consistent with granular cell tumor instead of the suspected sarcoma." (PMID 17355632, 2007). "One notable work on sarcoma CTCs detection using immunofluorescence was reported recently, in which the commercially available Abnova Cytoquest was used to isolate cell-surface vimentin (CSV)-positive CTCs (defined as CSV+CD45−) from pediatric sarcoma patients to assess overall survival." (PMID 38811642, 2024). "High expression of CD44, EMP3 and VIM may be useful to distinguish the tumors from CIC-rearranged sarcoma." (PMID 36964296, 2023). "Tumor histology may show a similar appearance to PSS, so to differentiate PSS from other sarcomas, the immunohistochemistry for vimentin, BCL-2, CD99, and TLE1 are common positive markers." (PMID 37170363, 2023). "In mammals, vimentin is a common immunohistochemical marker for distinguishing between epithelial and mesenchymal tissues and identifying tumors exhibiting a mesenchymal phenotype, such as sarcomas." (PMID 37760333, 2023). "We also diagnosed two cases of poorly differentiated sarcoma expressing vimentin and α-SMA." (PMID 35454212, 2022). "Withaferin-A (WFA), a naturally derived bioactive compound, is a vimentin inhibitor, which could be a promising drug against vimentin-expressing sarcoma cells." (PMID 34022967, 2021). "However, a subset of sarcoma cells showed cytokeratin+/vimentin+ expression, indicating an intermediate state between typical carcinomas and sarcomas." (PMID 34172714, 2021). "On the contrary, we could change the marker to vimentin or S-100, commonly used in sarcomas to detect circulating sarcoma cells, which poses some really interesting questions, despite our not having enrolled sarcoma patients in this study." (PMID 34064011, 2021). "However, it should be noted that the process of MET in sarcoma is characterized by increased expression of epithelial-like markers such as E-cadherin, whereas the typical mesenchymal markers including vimentin remain abundantly expressed in the sarcoma cells." (PMID 34022967, 2021). "In malignant pleural mesothelioma (MPM) and pulmonary sarcomatoid carcinoma (PSC), which are thoracic mesenchymal malignant tumors, programed cell death ligand‐1 (PD‐L1) was positive in the vimentin‐positive part or the sarcomatoid area, found to be clinicopathologically significant." (PMID 34655161, 2021). "Reactivity for vimentin, desmin, muscle specific actin and S-100 protein was observed in poorly differentiated areas in addition to the expected positivity of each histologic subtype of sarcoma." (PMID 33235646, 2020). "However, in contrast to carcinoma cells, sarcoma cells are mesenchymal cells basically expressing vimentin." (PMID 31215499, 2019). "Cell lines were validated via vimentin expression or growth as subcutaneous sarcomas in nude mice." (PMID 30498397, 2018). "A definitive diagnosis can only be made when an osteogenic sarcomas arising from the underlying bones is excluded, and immunohistochemical tests show positivity for vimentin with absence of epithelial, neural, muscular, and other markers." (PMID 23691385, 2013). "Here, negative IR on CEA and the morphological picture seem to have been crucial for the MM diagnosis, since there may be positive IR of both Pan-cytokeratin and Vimentin in carcinomas and sarcomas." (PMID 20602796, 2010).
sarcoma (continued). "Histopathology revealed characteristic GCTs with positive immunostaining for neural marker (S-100) and negative immunostaining for epithelial (cytokeratin, Cam 5.2, AE/A13), neuroendocrine (neuron specific enolase, chromogranin A, and synaptophysin) and sarcoma (desmin, vimentin) markers." (PMID 17355632, 2007). "Furthermore, the addition of fluorescent labeling of Vimentin (VIM), a previously reported sarcoma cell surface biomarker, could enabled the dual visualization of total plasma EVs and VIM-positive EVs from OS patients’ plasma." (PMID 34527582, 2021). "In addition to being positive for vimentin, these sarcomas may be positive for either SMA and/or desmin, resulting in desmin(+)/SMA(−), desmin(−)/SMA(+) and desmin(+)/SMA(+) immunophenotypes." (PMID 25624890, 2015). "The neuroendocrine tumor was positive for chromogranin and synaptophysin; GIST showed immunopositivity for CD117 and SMA; Synovial sarcoma showed immunoexpression of panCK, Bcl2 and TLE1; and epithelioid angiomyolipoma was positive for vimentin, CK7 and HMB45." (PMID 38235567, 2024). "In this case, atypical vimentin-positive spindle cell and CD68-positive giant cell in the sarcoma component are similar to one case of sarcoma and one case of osteosarcoma nodule.Sarcomatoid nodules were sometimes weakly positive for CK." (PMID 38903727, 2024). "Further analysis of differentially methylated regions between tumors within the novel group and CIC-rearranged sarcoma showed aberrant methylation patterns, including promoter region hypomethylation amongst others of CD44, EMP3, and VIM in these tumors." (PMID 36964296, 2023). "Thoracic mesenchymal malignant tumors such as MPM and PSC tend to have “mesenchymal” characteristics, such as having a sarcomatoid morphology or having vimentin, a medium‐diameter filament peculiar to stromal cells, in the cytoskeleton." (PMID 34655161, 2021). "Moreover, the expression of CDH1 (E-cadherin) decreased, and the expression of CDH2 (N-cadherin) and VIM (vimentin) increased in the dECM compared to 2D culture with plastic dishes and culture on Matrigel, which is a crude extract of the basement membrane formed by Engelbreth-Holm-Swarm sarcomas." (PMID 31013621, 2019). "However, it should be taken into account that some mesenchymal malignancies such as Ewing's sarcoma and epithelioid sarcoma may express cytokeratin so that it can be helpful to utilize a panel of antibodies, including anti-vimentin usually expressed in sarcoma cells." (PMID 21961623, 2011). "Eighty-six poorly-differentiated neoplasms were categorized as carcinomas, sarcomas, lymphomas or neuroendocrine cancers with a panel of 7 antibodies (cytokeratin AE1/AE3, vimentin, desmin, myogenin, leukocyte common antigen and neuron-specific enolase)." (PMID 21044352, 2010). "Even after the detection of the mesenteric primary, the patient was initially treated as a mesenteric sarcoma as histopathology showed a sarcoma which was positive for CD34 and vimentin antigen." (PMID 17105654, 2006). "vimentin as an exclusive marker on sarcoma circulating tumor cells regardless of the tissue origin of the sarcoma." (PMID 40012551, 2025). "The SMARCA4-deficient carcinosarcoma reported in this study is an unclassified pleomorphic sarcoma, which is immunoreactive to the stromal marker Vimentin but non-immunoreactive to the epithelial markers CK, EMA." (PMID 41170461, 2025). "GCTs are usually negative for cytokeratin (Cam 5.2 and AE1/AE3), vimentin and desmin, which are epithelial and sarcoma antigens." (PMID 38959614, 2024). "In IHC, undifferentiated cells typically express broad lineage carcinoma (PCK) and sarcoma (vimentin and desmin) markers and exhibit the absence of E-Ca." (PMID 38389041, 2024). "In sarcoma, the expression levels of ANXA1 were positively correlated with those of MMP9 (r=0.204, P=9.43e-04), COL1A2 (r=0.349, p=8.87e-09), S100A4 (r=0.574, P<0.001), VIM (r=0.48, P<0.001) and S100A11 (r=0.638, P<0.001)." (PMID 36988561, 2023).